PARP1 (poly(ADP-ribose) polymerase 1)
Diseases named in the same sentence as PARP1 in open-access papers (continued):
Sharing a sentence is not in itself a finding about the gene and the disease.
cancer (continued). "Immunofluorescence signalling levels of PARP1 and its substrate PAR were quantified in cancer areas in corresponding paired slides." (PMID 28851861, 2017). "PARP-1 dependent PARylation event directs the recruitment of helicase, such as ALC1 (amplified in liver cancer 1) to chromatin and nucleosomes." (PMID 28978184, 2017). "PARP1 inhibition, which blocks the JNK–PARP1–JNK loop and ERK-mediated anti-apoptotic protein expression, will result in cancer apoptosis." (PMID 28991194, 2017). "Last but not least, we provide an example on the applicability of an Arabidopsis thaliana—based plant system monitoring the role of cancer-related DNA repair genes BRCA1, BARD1 and PARP1 in processing DNA lesions." (PMID 28587301, 2017). "Several targeted therapeutic agents are currently under clinical investigation, such as PARP1 inhibitors, PI3K inhibitors, MEK inhibitors, and inhibitors of the cancer stem-cell population." (PMID 29312562, 2017). "Intensive research on PARP-1's mechanism of action in DNA repair led to the concept that defective PARP-1 functions result in genomic instability and cell death fueling the idea of the use of pharmacological PARP-1 inhibitors in anti-cancer therapies." (PMID 28430591, 2017). "Inhibitors of PARP1, a protein which participates in DDR, require defective HR for their anti-cancer activity." (PMID 29090014, 2017). "Poly (ADP-ribose) polymerase 1 (PARP-1) is a crucial contributor to exacerbate ischemia and reperfusion (IR) injury and cancer process." (PMID 29179487, 2017). "It indicated that PARP1 gene promoted the proliferation of NSCLC, whose role was consistent in others malignant tumor." (PMID 29152079, 2017). "Furthermore, PARP1-mediated carcinoma metastasis may be in gene transcription manner." (PMID 28991194, 2017). "Investigation of PARP1 expression level in various tumors is essential to evaluate potential therapeutic effects, and side effects of PAPR1 inhibitors on each subtype of carcinomas." (PMID 28991194, 2017). "Knockdown of either ERK3 (siCtrl/shERK3), TDP2 (siTDP2/shGIPZ) or both (siTDP2/shERK3) greatly increased the levels of cleaved PARP-1, suggesting that ERK3 and TDP2 also protects cancer cells against etoposide-induced apoptosis." (PMID 26701725, 2016). "Along with reduced anti-apoptotic transcription, Sam68 knockdown sensitized cancer cells to CPT- or γ-irradiation-induced apoptosis, as conveyed by the boosted cleavage of PARP1 and Caspase-3." (PMID 27458801, 2016). "We here propose that the persistent activation of PARP1 and the accumulation of DNA damage beyond a certain threshold of physiological DNA repair limit, as well as the induction of autophagy, might create a positive niche for tolerance phenomena and the establishment of cancer cells." (PMID 27050370, 2016). "PARP-1, the most abundant and best-characterized member of the PARP superfamily, has emerged as a promising molecular target for the treatment of cancer in the past decade." (PMID 27304949, 2016). "We previously reported that poly-ADP ribose polymerase 1 (PARP1) is overexpressed in SCLC, identifying PARP as a potential therapeutic target in this cancer." (PMID 27055253, 2016). "Poly(ADP-ribose) polymerase 1 (PARP1) is a key player in DNA repair, genomic stability and cell survival and it emerges as a highly relevant target for cancer therapies." (PMID 26950694, 2016). "PARP1 is overexpressed in many human cancers, particularly SCLC, and is being developed as a target in the treatment of a number of cancers including those of the ovary, breast, prostate and lung." (PMID 27055253, 2016). "Taken together, our findings provided an advanced NTP regimen for cancer treatment by combining NTPO treatment with chemical adjuvants for the inhibition of ATR- and PARP1-activated DNA damage responses, and circadian timing of treatment." (PMID 27145275, 2016).
cancer (continued). "Given that PARP1 has an important role in DDR, a novel therapeutic targeting PARP1 has been developed to treat cancers through increasing tumor sensitivity to chemotherapeutic agents and also through inducing “synthetic lethality” in cells." (PMID 27240471, 2016). "Henceforth, PARP-1 is an indispensible role player in tumour cell development and PARP-1 targeted therapy can positively predict the outcome in cancer therapy." (PMID 25606064, 2015). "Our studies further suggest that synthetic lethality interaction (PARP1 and BRCA1/BRCA2) only exist in certain types of cancers." (PMID 25865228, 2015). "Due to the crucial role of PARP-1 in the pathophysiology of different diseases, multiple clinical trials using PARP inhibitors have been performed, primarily for the treatment of cancer." (PMID 26339143, 2015). "PARP1 is activated within a few seconds after DNA damage to interact with and PARsylate (add poly ADP ribose) IKK gamma, and which promote cancer cell survival via NF- κB activation." (PMID 26540566, 2015). "In conclusion, this study is the first attempt to define the autoantibodies to synthetic lethal interactions (PARP1 and BRCA1/2) which would be useful in developing therapeutic targets for treatment of certain types of cancer." (PMID 25865228, 2015). "Thus, miR-223 may serve as an endogenous PARP-1 inhibitor for cancer treatment." (PMID 26221610, 2015). "The antibody responses to PARP1, BRCA1, and BRCA2 had strong reactivity in representative cancer sera compared to normal controls." (PMID 25865228, 2015). "FK866 primes cancer cells for cell death by lowering NAD+/NADH pools and prevents recovery by inhibiting NAD+ synthesis from nicotinamide liberated by activated PARP1." (PMID 25590809, 2015). "In particular inhibitors to DNA-PKs (NHEJ), RAD51 (HR), PARP1/2 (HR, altNHEJ, BER), CHK2 (HR, altNHEJ), CHK1 (HR, NER) are currently under clinical investigation in various cancers." (PMID 24809299, 2014). "We found, for instance, that 6 cancer-related targets changed their expression levels: HSPD1, PARP1, XRCC5, PRDX2, MTA2 and FASN." (PMID 24801752, 2014). "Considering that PARP-1 functionally interacts with XRCC1 in BER processes, we performed a gene-gene interaction analysis of the five studies that reported joint effects between PARP1 Val762Ala and XRCC1 Arg399Gln on cancer risks." (PMID 24853559, 2014). "We also demonstrate synergistic inhibition of PARP-1, combining MGBLs with conventional NAD+-dependent inhibitors in human cancer cells." (PMID 24504413, 2014). "Because RBP functions can be regulated by manipulating the activities of PARP and PARG, PARP1 and PARG inhibitors are potential therapeutics to treat a variety of RBP-related cancer and neurodegenerative diseases." (PMID 23921685, 2013). "NAD is an important cofactor for poly(ADP-ribose) polymerase 1 (PARP1) which is involved in DNA repair and therefore cancer cells are more sensitive to NAMPT inhibition than normal cells." (PMID 23308217, 2013). "Very interestingly, in our cancer cells, AKT activation related to PARP1 inhibition was unable to modulate pro-survival signals, probably because the downstream pathway was interrupted at the level of its effector mTOR." (PMID 23301673, 2013). "By using GST-HOXB7-Sepharose affinity chromatography with cell extracts from several breast epithelial cells, both normal (MCF10A, MCF12A) and cancer (SKBR3), we identified PARP-1 as a HOXB7-interaction partner." (PMID 22844406, 2012). "Pristimerin has been shown to induce mitochondrial cell death in human cancer cells, and the ROS dependent activation of both Bax and poly (ADP-ribose) polymerase-1 (PARP-1) is critically required for mitochondrial dysfunction." (PMID 22069560, 2010). "By selectively binding to and “trapping” PARP1 on damaged DNA, AZD9574 prevents base excision repair (BER), leading to the accumulation of DNA strand breaks and genomic instability, ultimately triggering cancer cell death (apoptosis)." (PMID 41510186, 2026).
cancer (continued). "PARP-1 and COX-2 have played important roles in several carcinomas, representing potential therapeutic targets; natural products have constituted interesting alternatives in cancer research, and complementary computational methods are relevant tools for the proposal of new molecules." (PMID 41683446, 2026). "BRCA mutated cancer cells, when treated with PARPi cannot repair DNA neither via Homologous Recombination (BRCA dependent) nor via Base Excision Repair (PARP1 dependent), which results in cell death." (PMID 40437523, 2025). "In addition, cancer-derived exosomes can deliver CRISPR/Cas9 to OC cells, suppress PARP-1, trigger apoptosis, and increase cisplatin sensitivity." (PMID 40369674, 2025). "• Exertion of anticancer effects through 3 major pathways: apoptosis (BIRC3, BIRC5, caspase-8, caspase-9, and PARP1), transcriptional dysregulation in cancer (CDKN1A, CDKN1B, MMP9, MYC, JUN, and RELA), and cancer progression (caspase-3, CCND1, CTNNB1, VEGFA, and Wnt-1)." (PMID 39181121, 2025). "The modulation of pathways involved in cancer metastasis (MMP9), inflammation (PTGS2), cell survival (AKT1), and DNA repair (PARP1) suggests that these compounds could serve as multitargeted therapies, providing an advantage over single-target drugs." (PMID 40283891, 2025). "Despite auranofin having several known modes of action in the cancer cell, each of them individually has an IC50 in the micromolar range (including inhibition of PARP‐1 DNA‐dependent activity), which is far too high when compared with EC50 = 12.4 nm found in our study." (PMID 41230800, 2025). "Targeting PARP1 [Poly(ADP-Ribose) Polymerase 1] for synthetic lethality in preclinical model and clinical setting is therapeutic strategy and approved for patient treatment for several types of cancer." (PMID 41568291, 2025). "Altogether these results align with the notion that the PARP1 trapping activity of PARPi drives their efficacy in BRCA1m cancer cells, regardless of their selectivity or PARylation inhibition potency." (PMID 41459749, 2025). "It is believed that PARP1 overexpression in HNSCC results primarily from increased DNA damage in genetically unstable cancer cells, rather than from the activation of specific oncogenic pathways." (PMID 40864763, 2025). "Excessive activation of PARP1 depletes significant levels of NAD+, leading to an imbalance in intracellular energy metabolism and increased oxidative stress, which inhibits the growth of cancer cells." (PMID 41219748, 2025). "Molecular docking and Prime MM-GBSA screening of seventeen cancer-related protein targets, including Human Double Minute 2 protein (HDM2), DNA methyltransferase-1 (DNMT1), Protein Kinase B (AKT2), and Poly (ADP-ribose) polymerase 1 (PARP-1), were conducted." (PMID 40575462, 2025). "Previous studies have identified PARP‐1 as a physical interaction protein of the ETS fusion factors, Fli1 and Erg, and have considered these ETS fusion proteins as predictors of sensitivity to PARPi in many cancers." (PMID 39778077, 2025). "Accordingly, elucidating the distinct regulatory roles of CSB in SSBR-mediated by PARP1 and PARP2 might uncover novel cancer therapeutic strategies that maximize PARPis’ efficacy with reduced toxicity to improve patient outcomes in cancer treatment." (PMID 39996712, 2025). "Yet, inhibition of PARP‐1 by Au(I) compounds has never been explored as a potential mechanism of cancer suppression." (PMID 41230800, 2025). "Primarily, targeting only PARP1, and not PARP2, is sufficient for efficacy in HRR-deficient cancer cells." (PMID 41459749, 2025). "PARP1 also exerts context-dependent effects: it promotes apoptosis to eliminate DNA-damaged cells early in tumorigenesis, but excessive activation depletes NAD+ and ATP, triggering parthanatos and inhibiting cancer progression." (PMID 41460301, 2025). "The significance of PARP1 in the DDR, and as a key drug target in cancer, is widely acknowledged." (PMID 41297801, 2025).
cancer (continued). "PARP‐1's role in tumor progression has been thoroughly characterized, which led to the development of PARP inhibitors for the treatment of various types of cancer." (PMID 40703196, 2025). "While PARP1 inhibitors such as Veliparib and Olaparib—widely used in cancer therapy—have shown promise in rescuing TDP-43-induced cell death in ALS models, their broad inhibition of PARP1 raises concerns due to the enzyme’s essential roles in DNA repair and transcriptional regulation." (PMID 41385186, 2025). "Hence, targeting the BER pathway—specifically PARP1 and PARP2—forms the basis for the “synthetic lethality” mechanism that the PARP inhibition strategy utilizes for the treatment of those cancer subsets with HRD." (PMID 40573300, 2025). "Furthermore, studies have shown activation of PARP-1 and NOX2 promotes migration of several cancer cell types." (PMID 40722879, 2025). "Similarly, another key regulatory enzyme associated with the repair of single-stranded breaks (SSBs), poly (ADP-ribose) polymerase 1 (PARP1), has been found to be overexpressed in multiple cancers." (PMID 40149342, 2025). "Our findings provide a mechanistic understanding of why cancer cells rely on PARP1 when XRN2 is absent and strengthen the translational aspect of targeting XRN2 cancer vulnerabilities using PARP inhibitors." (PMID 38339346, 2024). "Although BRCA mutations often correlate with elevated PARP1 levels, not all BRCA-mutated cancers respond effectively to PARP inhibitors, and some non-BRCA-mutated cancers also exhibit high PARP1 expression." (PMID 39768978, 2024). "Alternatively, it is possible that talazoparib quickly killed these cancer cells with naturally insufficient PARP1/2 activity by study day 8, leaving non-viable tumor tissue at the time of the on-treatment biopsy." (PMID 38010394, 2024). "In vitro tests on MP41 (BAP1 positive) and MP46 (BAP1 negative) cancer cell lines using inhibitors pamiparib (PARP1) and Ymu1 (DTYMK) demonstrated significant cytotoxic effects." (PMID 39195238, 2024). "PARP1 and DHX9 are key players in genomic stability and cancer." (PMID 38247850, 2024). "Taken together, these findings reveal a mechanistic link between HMGA1 and PARP1 in regulating cell responses to DNA damage and suggest that targeting HMGA1 could be a promising strategy to increase cancer cell sensitivity to olaparib." (PMID 39690136, 2024). "The nuclear protein poly (ADP-ribose) polymerase-1 (PARP-1) is well characterized for pleiotropic functions in diverse pathophysiological processes such as DNA repair, transcription, apoptosis, and inflammation, and is overexpressed in many cancers." (PMID 39433869, 2024). "Advocated by the polypharmacology concept, recentevidence discovered that a significantly synergistic effect in increasingthe death of cancer cells was observed by simultaneously perturbatingthe enzymatic activities of bromodomain-containing protein 4 (BRD4)and PARP1." (PMID 39292752, 2024). "Therefore, PARP1 and PARP2 inhibition provides cancer-targeted potency by disrupting the DNA repair processes in cancer cells." (PMID 38099989, 2024). "Collectively, these studies may encourage the development of therapeutic approaches differentially targeting PARP1 and PARP2, especially in ALT cancers and more generally in cancer cells harboring high levels of replication stress." (PMID 38565848, 2024). "The most pronounced differences between the cell lines included the induction of cell death (via the activation of caspase 7 and caspase 9 and PARP1 cleavage) and the inhibition of the estrogen response signaling pathway in the estrogen receptor-positive MCF7 cancer cell line." (PMID 39468555, 2024).
cancer (continued). "Further analysis using tSNE visualization confirmed that HMGA1 and PARP1 expression was significantly higher in cancer cells compared with adjacent noncancerous tissues, consistent with the IHC results." (PMID 39690136, 2024). "The contribution of PARP-1 in cancer initiation and progression is not totally understood despite it being overexpressed in several human cancer types." (PMID 36902215, 2023). "PARP-1 is one of the main participants in DNA repair, playing a key role in terms of Base Excision Repair (BER) and DNA Single-Strand Break (SSB) repair; thereby emerging as an attractive target in anti-cancer drug discovery projects." (PMID 37762072, 2023). "Nevertheless, there is evidence that pharmacological inhibition of poly(ADP-ribose) polymerase-1 (PARP-1), a key DNA repair enzyme, specifically sensitises ETS-expressing cancer cells to DNA damage and limits tumour progression by leading some of the cancer cells to death." (PMID 37686260, 2023). "The combination of PARP-1 and HSP inhibition with HR inactivation via hyperthermia may be a promising therapeutic in cancer treatment." (PMID 36900195, 2023). "Given PARP-1’s critical role in DNA damage repair, using PARP-1 inhibitors to enhance the efficacy of anti-cancer treatments could increase tumor cell sensitivity to radiotherapy or chemotherapy." (PMID 37351512, 2023). "Cancers that have lost the essential BRCA genes utilize WRN helicases to prevent stalled replication fork degradation and rely on DNA repair facilitated by PARP1 and PARP2." (PMID 37627183, 2023). "Similarly, PARylation of transcription factor STAT3 by PARP1 has been reported to inhibit STAT3 transcriptional activity, and decrease the expression of PD-L1 in cancer cells." (PMID 37582914, 2023). "Through its combined AP/dRP lyase activity and its PARP1-promoting function, HMGA2 supports cellular capacity for BER and single-stranded (ss) DNA repair, which are both particularly important in cancer cells undergoing oxidative DNA damage or those exposed to alkylating drugs." (PMID 36980621, 2023). "Thus, in addition to the potential clinical uses of CDEAH for cancer therapy, CDEAH can be used as a tool compound to better understand NER and PARP1-dependent BER pathways in detail." (PMID 37554969, 2023). "Since EVI1 is upregulated in certain cancer types with chromosomal instabilities and since single strand DNA repair mechanisms such as PARP1 are often upregulated in HGSOC, we investigated the frequency and prognostic importance of EVI1 and PARP1 in HGSOC." (PMID 37525239, 2023). "Notably, miR-221-3p has been reported to act as a tumor promoter in multiple types of cancers, involved in tumor invasion, metastasis, proliferation and chemotherapy resistance by regulating the expression of target genes such as VASH1, PARP1, RB1." (PMID 36991449, 2023). "According to the proteomics, although the expression of TOP2A was also reduced for this comparison, there were multiple other changes in the DNA damage recognition/repair machinery that affected the overall outcome (e.g., reduction in breast cancer gene 2, BRCA2 and gain in PARP1)." (PMID 37242727, 2023). "The results, however, indicate that not all cell lines were sensitive to PARP1 degradation, and protein degradation appears to be strictly dependent on the type of cancer." (PMID 37175377, 2023). "By understanding and manipulating LLPS of PARP1, it might be possible to increase the effectiveness of PARP inhibitors or develop alternative approaches to target the DNA repair machinery in cancer cells." (PMID 37705755, 2023). "Bioinformatics analyses of Gene Expression Profiling Interactive Analysis (GEPIA), Genomics of Drug Sensitivity in Cancer (GDSC) and Cancer Cell Line Encyclopedia (CCLE) datasets were applied to explore the relationship between YB-1/PARP1 protein levels and CDK4/6i IC50." (PMID 38037159, 2023). "PARP1 is the most abundant and well-studied PARP, and it is highly expressed in cancer cells." (PMID 37667522, 2023).